SYP (synaptophysin)
Diseases named in the same sentence as SYP in open-access papers (continued):
Sharing a sentence is not in itself a finding about the gene and the disease.
tumor (continued). "Patchy expression of chromogranin and focal expression of synaptophysin was noted in the malignant cells of the tumor specimen, comprising ∼10% and <5% of the total tumor cellularity, respectively." (PMID 28835367, 2017). "After surgery, immunostaining of a tumor specimen showed expression of the tumor makers chromogranin and synaptophysin." (PMID 29258609, 2017). "Immunohistochemically, tumor cells usually show positive reactivity for neuroendocrine markers, including synaptophysin and chromogranin A. In addition, these tumors generally show positive reactivity for ER and PgR." (PMID 28105053, 2016). "Immunohistochemical staining of the specimen identified diffuse positivity for keratin, CD56, and synaptophysin in the tumor cells, which is consistent with NEC." (PMID 27842605, 2016). "To exclude the possibility of the occurrence of mixed adenocarcinoma, neuroendocrine features, or both, we performed an independent pathology review in terms of architecture, tumor grade, and chromogranin, synaptophysin, and CD56 immunoreactivity by IHC." (PMID 26684240, 2016). "Tumor cells were positive for synaptophysin (reactivity rate 100%) and chromogranin A (reactivity rate 50%)." (PMID 27840759, 2016). "In this study, we demonstrate that immunohistochemical detection of FAIM2 expression outperforms the known NE tumor marker synaptophysin in SCLCs and atypical carcinoids." (PMID 27677402, 2016). "IHC using synaptophysin, an established NE tumor marker, was performed in parallel to compare to the performance of IHC using FAIM2." (PMID 27677402, 2016). "According to the definition, NECB is a tumor expressing neuroendocrine (NE) markers in more than 50% of the cell population, synaptophysin and/or chromogranin." (PMID 27840759, 2016). "The tumor cells showed positive immunoreactivity for synaptophysin, chromogranin A, ER, PgR, and bcl-2 and negative (or almost negative) immunoreactivity for HER-2." (PMID 28105053, 2016). "In contrast to the majority of these tumours, this biopsy was immunohistochemically positive for chromogranin A, and synaptophysin and Ki-67 index was 50% and the tumour was diagnosed as poorly differentiated neuroendocrine carcinoma of the oesophagus." (PMID 26955490, 2016). "Immunohistochemically, the tumor cells expressed neuroendocrine markers, such as chromogranin A, synaptophysin, and/or CD56." (PMID 27457076, 2016). "The median size of the tumours was 1.5 cm (range: 0.1–16.5 cm), of which 87.3 % (n = 110) and 98.4 % (n = 124) were positive for chromogranin A (CgA) and synaptophysin respectively." (PMID 26911576, 2016). "Immunohistochemical staining showed that the tumor cells were synaptophysin- and NeuN- positive but GFAP- and CK-negative." (PMID 26376790, 2015). "The tumor cells were positive for chromogranin A, synaptophysin, CD99, cytokeratin 19, pan-cytokeratin and β-catenin, and also showed diffuse immunoreactivity for AFP and human chorionic gonadotrophin." (PMID 25886790, 2015). "One of the most interesting features of the present case was that the tumor cells were focally positive for synaptophysin." (PMID 26187280, 2015). "For the other tumor markers (synaptophysin, chromogranin-A, NCAM, CK5/6, K903, p40, and p63), immunohistochemical expression did not correlate significantly with location of the primary tumors." (PMID 26705222, 2015). "The gastropancreatic neuroendocrine neoplasms (GEP-NEN) are a heterogeneous group of tumours characterized by the expression of the neural antigens such as chromogranin A or synaptophysin." (PMID 25933800, 2015). "Immunohistochemical examinations showed that the tumor cells were synaptophysin- and NeuN-positive but GFAP-negative." (PMID 26376790, 2015). "Immunohistochemically, the tumor cells stained positive for synaptophysin and chromogranin A, which is consistent with human panPETs." (PMID 26192435, 2015). "Immunohistochemically, there was positive staining for synaptophysin, CD 56, and S-100 in the tumour cells." (PMID 26064749, 2015).
tumor (continued). "Brain markers such as GFAP (glial fibrillary acid protein), VEGF (vascular endothelial growth factor) and SYP (synaptophysin) and tumor formation were analyzed." (PMID 25637958, 2015). "The tumor cells displayed diffuse positivity for vimentin, inhibin, synaptophysin, and neuron-specific enolase (NSE)." (PMID 26376405, 2015). "Immunohistochemically, there was diffuse and strongly positive staining for synaptophysin, CD 56, and S-100 in the tumour cells." (PMID 26064749, 2015). "The tumor cells show strong immunoreactivity for synaptophysin, variable staining for NeuN, whereas GFAP stains are typically negative, which further confirmed that they were differentiating into neurons." (PMID 26376790, 2015). "In our case, the tumor showed positivity for desmin and negativity for all the other IHC markers like synaptophysin, chromogranin, S100, calretinin, Inhibin, and pan keratin." (PMID 25685588, 2015). "The tumor cells were identified to be positive for synaptophysin, chromogranin A and cluster of differentiation 56, but were negative for Ki-67." (PMID 24765196, 2014). "All of the 29 tested carcinomas were negative for chromogranin A and one of the 29 cases stained moderately and focally (<10% of tumor cells) for synaptophysin." (PMID 24701575, 2014). "The vacuolated cells were immunoreactive for synaptophysin, while the fibrillary tumour matrix showed decreased synaptophysin expression compared to the adjacent cortex." (PMID 24444358, 2014). "The tumor was strongly and diffusely positive for synaptophysin and chromogranin, confirming neuroendocrine differentiation." (PMID 25525544, 2014). "All tumours showed strong immunostaining for CgA and synaptophysin in the majority of neoplastic cells and displayed very low proliferative activity corresponding with G1 (Ki-67 index ≤2)." (PMID 24695372, 2014). "The mitotic rate was <2 mitoses/50 HPF (High-power-field), and the tumor cells were positive for chromogranin and synaptophysin with a low proliferation rate by Ki67 of 1%." (PMID 25494951, 2014). "A monomorphous neoplasia composed of small, round synaptophysin-positive cells with uniform distribution was observed, with a very low proliferation rate (1-2%); GFAP staining showed the presence of scattered reactive astrocytes." (PMID 25524219, 2014). "The tumor showed proliferation of small, round, synaptophysin-positive cells with a prevalent ribbon-like pattern of growth and scattered more classical monomorphous areas; MIB-1 was about 3-4%." (PMID 25524219, 2014). "Apart from the characteristic “neuroendocrinal” morphology noted on cytology and histology, MCT is immunopositive for markers such as calcitonin (most specific tumour marker), synaptophysin, chromogranin, and CD56." (PMID 25478248, 2014). "One of 15 stained HER2 amplified carcinomas showed strong focal chromogranin A expression in only <1% of tumor cells and two of the 15 stained cases showed moderate to strong focal synaptophysin staining in <1% and <10% of tumor cells respectively." (PMID 24701575, 2014). "Immunohistochemical staining revealed that the tumor cells were chromogranin A- and synaptophysin-positive, and carcinoembryonic antigen-, hepatocytic antigen- and α-fetoprotein-negative." (PMID 24944650, 2014). "One of them was small cell NEC, with only focal expression of CgA and synaptophysin and with high proliferative activity of tumour cells (Ki-67 index exceeding 50%), corresponding with G3." (PMID 24695372, 2014). "Tumor type was validated by immunostaining of chromogranin-A and synaptophysin expression and tumor grade was analyzed by Ki-67 proliferation index." (PMID 24915894, 2014). "The tumor often stains positive for neuroendocrine markers such as synaptophysin, CD 56, and chromogranin A." (PMID 25057271, 2014).
tumor (continued). "Immunohistochemically, the tumor was positive for cytokeratin, epithelial membrane antigen, cluster of differentiation 117, synaptophysin and thyroid transcription factor-1, which indicated that the tumor was a SCC of the parotid gland." (PMID 25120705, 2014). "The tumour cells showed strong diffused immunoreactivity for vimentin, synaptophysin, CD56 and inhibin." (PMID 24602387, 2014). "A right iliac crest bone marrow biopsy was performed, and it showed 60% infiltration with GFAP-positive and nestin-positive tumor cells, while synaptophysin was focally positive." (PMID 25563358, 2014). "Tumour cells were vimentin, synaptophysin, calretinin, inhibin, CD56 and melan A-positive, consistent with the literature." (PMID 24602387, 2014). "Histological examination revealed a rosette arrangement of the tumor cells by HE staining and immunohistochemical study revealed positive CD 56, synaptophysin, and chromogranin A (LCNEC)." (PMID 23653657, 2013). "The tumor had immunohistochemically strong staining for synaptophysin, CD56, and in some areas, chromogranin." (PMID 24099413, 2013). "A rosette-like structure was also observed with an extremely high rate of mitosis.Immunohistochemical analysis demonstrated that tumor cells were positive chromogranin A, synaptophysin, and CD56." (PMID 23653657, 2013). "The present tumor was immunocytochemically characterized by S-100 reactivity of the spindle cells and synaptophysin positive in other areas." (PMID 24073351, 2013). "Tumor cells infiltrating lung, liver and lymph node tissues also stained positive for synaptophysin." (PMID 23620793, 2013). "Immunohistochemistry revealed a strong positive reaction for the neuronal marker synaptophysin and for the antibody to βIII Tubulin demonstrating mostly immature neurons in 100% of the tumor cells." (PMID 23840986, 2013). "Immunohistochemical expression of CD56, synaptophysin, and chromogranin A was strongly positive in the tumor cells." (PMID 24171129, 2013). "The tumor cells in case 1 were immunopositive for synaptophysin and chromogranin in a scattered fashion and for NSE and CD56 in a diffuse manner." (PMID 24137427, 2013). "Immunohistochemistry revealed that the tumor was positive for the presence of synaptophysin and chromogranin with one metastatic lymph node." (PMID 24138700, 2013). "Histopathological examination revealed tumor nests with typical morphology of well-differentiated neuroendocrine tumor that expressed chromogranin and synaptophysin." (PMID 23401809, 2013). "Our immunohistochemical analysis revealed that the tumor was positive for Chromogranin A, vimentin, S-100, synaptophysin, thus providing a histopathological basis for a correct diagnosis of nonchromaffin paraganglioma of the retroperitoneum in the patient." (PMID 23537060, 2013). "The tumor cells are stained positive for synaptophysin, chromogranin A, and neuron specific enolase (NSE)." (PMID 24062959, 2013). "The neuroendocrine markers synaptophysin and neuron-specific enolase were found to be positive in almost all the tumor cells." (PMID 23738176, 2013). "Immunohistochemical stainings revealed tumor cells positive for chromogranin, synaptophysin, and neuron specific enolase." (PMID 23021468, 2012). "The tumor cells were positive for chromogranin A, synaptophysin, CD57, cytokeratin (Ck), and TTF1, but staining for CD 20 was negative." (PMID 23119202, 2012). "In consideration of the slow tumor progression, the low Ki-67 labelling index and the expression of CgA and synaptophysin, the diagnosis was ultimately changed to TC." (PMID 22269186, 2012). "All of the tumours were found to be diffusely positive for chromogranin A, synaptophysin and neuron-specific enolase with immunohistochemistry, confirming their neuroendocrine origin." (PMID 22476195, 2012). "IHC stains showed focal moderate tumor immunoreactivity for synaptophysin consistent with focal neuroendocrine differentiation." (PMID 22284391, 2012).
tumor (continued). "Mice whose tumors were positive for synaptophysin had a significantly younger age of tumor detection as well as an earlier age of death when compared to the NE negative mice." (PMID 23304522, 2012). "Immunohistochemical characterization revealed expression of synaptophysin and chromogranin in tumor cell nests and peripheral S100 protein expression in sustentacular cells." (PMID 22344361, 2012). "Markers to identify the neuro-endocrine origin of the second tumor include chromogranin, synaptophysin and neurone specific enolase." (PMID 20205830, 2010). "Tumor cells of both epithelioid and ganglion-like cell types showed positive reactivity for synaptophysin, somatostatin, and CD56." (PMID 20444291, 2010). "The adrenal phenotype of this tumor was verified by the immunopositivity for a panel of immunohistochemical markers, namely, Melan-A, synaptophysin, calretinin, particularly on the well differentiated carcinomatous component." (PMID 20687934, 2010). "Immunoperoxidase staining for chromogranin A, neuron specific enolase, and synaptophysin were positive in nearly 100% of the urethral tumor cells, showing a granular cytoplasmic distribution." (PMID 20205830, 2010). "Neuroendocrine differentiation of the tumor cells was confirmed in each instance by immunohistochemical analysis for neuron-specific enolase, chromogranin A, and/or synaptophysin and/or electron microscopy studies showing neurosecretory granules." (PMID 20205830, 2010). "The tumor cells were positive for neuroendocrine markers chromogranin, and synaptophysin as well as CD56 and Thyroid Transcription Factor-1 (TTF-1)." (PMID 20807418, 2010). "Both patients whose primary RCC tumour showed an immunopositivity for synaptophysin are still alive after 10 and 17 years follow-up." (PMID 20462442, 2010). "Immunohistochemically the tumor was positive to synaptophysin, neuron specific enolase (NSE), CD56 and TTF1." (PMID 21087512, 2010). "The two patients with synaptophysin immunopositive tumours showed an excellent RCC-specific survival." (PMID 20462442, 2010). "Tumor cells of the epithelioid cell type metastasizing at the lymph node showed positive reactivity for synaptophysin." (PMID 20444291, 2010). "The aim of this study was to clarify the extent of the immunoexpression of NE markers, serotonin, CD56, NSE, chromogranin A and synaptophysin in RCCs and their significance regarding the behaviour of these tumours." (PMID 20462442, 2010). "The pattern of neural differentiation is assessed by immunopositivity for HMB45, GFAP, NFP and synaptophysin has been compared in: [a] the general tumor [b] tumor-vascular complexes and [c] perimantle zone [PC] on serial frozen and paraffin sections." (PMID 21080952, 2010). "Staining for synaptophysin, a marker of primitive neurons was weak in both tumor types, but appeared to overlap with staining for PCNA." (PMID 20520772, 2010). "Immunohistochemical examination demonstrated that the tumor cells were positive for neuroendocrine markers, such as chromogranin, synaptophysin, and neural cell adhesion molecule (NCAM), suggesting that the lesion was a carcinoid." (PMID 19159493, 2009). "Immunohistochemically, the tumor cells were positive for major neuroendocrine markers, such as synaptophysin, NCAM (CD56), and chromogranin A (Fig. 2BCD)." (PMID 20062644, 2009). "We report the first case of a patient with precursor T-ALL/T-LBL who presented with cholestatic jaundice and aberrant tumor expression of synaptophysin." (PMID 19284608, 2009). "Immunohistochemically, tumor cells were positive for at least one of pan-neuroendocrine markers including chromogranin, synaptophysin, neuron-specific enolase, CD56, and glucagon." (PMID 27956948, 2009). "The tumor cells were positive for at least one of pan-neuroendocrine markers including chromogranin, synaptophysin, neuron-specific enolase, CD56, and glucagon." (PMID 27956948, 2009).
tumor (continued). "In the present series, the tumor cells were positive for at least one of pan-neuroendocrine markers including chromogran, synaptophysin, neuron-specific enolase, CD56, and glucagon." (PMID 27956948, 2009). "The endocrine cells in appendiceal tumour nests were chromogranin A-, somatostatin-, synaptophysin- (Figure." (PMID 18252007, 2008). "Staining for Chromogranin was positive in some cells and for Synaptophysin in most cells, indicating a degree of neuroendocrine activity of the tumor." (PMID 18442419, 2008). "The NEC portion of the neoplasm was positive for synaptophysin, chromogranin, NSE, pancytokeratin, and CAM 5.2." (PMID 17988399, 2007). "Immunohistochemically the tumor strongly reacted with synaptophysin, chromogranin, calcitonin, keratin 7, and NSE." (PMID 16048646, 2005). "Examination of the tumor by immunohistochemistry and electron microscopy indicated it to be neuroendocrine in nature, expressing synaptophysin and AE1/AE3, and containing dense core granules." (PMID 15310407, 2004). "Synaptophysin, stands out as the most specific tumor marker." (PMID 41589095, 2026). "Thus, although most NENs are positive for chromogranin A and synaptophysin: however, interpretation must always consider the degree of differentiation, histologic features, and biological behavior of the tumor." (PMID 41458541, 2025). "Immunohistochemically, the tumor cells were positive for chromogranin A and synaptophysin." (PMID 40852171, 2025). "Abdominal contrast-enhanced CT demonstrated a characteristic mesenteric mass, and immunohistochemical analysis of tumor tissue revealed positive staining for CgA and synaptophysin, with a Ki-67 proliferation index ranging from 3% to 20%, thereby classifying it as G2." (PMID 40324239, 2025). "Interestingly, tumours with SMARCA4 loss, a hallmark of poorly differentiated NSCLC, showed high expression of NE markers, particularly SYP." (PMID 41025426, 2025). "Neuron-specific enolase, synaptophysin, and S100 protein may also be expressed by tumor cells, depending on the degree of neuroectodermal differentiation." (PMID 41311764, 2025). "European Society for Medical Oncology practice guidelines mandate histological diagnosis in all the patients and suggest the reporting of morphology, grading, and immunohistochemical staining of chromogranin A (cgA) and synaptophysin for appropriate pathological diagnosis of the tumor." (PMID 41235383, 2025). "A potential explanation for the alternate conclusion could be the lower sensitivity of chromogranin A, as we found that 37% of tumours with NED stained for synaptophysin only, in keeping with the known superior sensitivity of synaptophysin." (PMID 39526928, 2025). "On immunohistochemical analysis, the tumor was positive for synaptophysin, CD56, GATA-3, and S100." (PMID 41179710, 2025). "An even more effective strategy could be the application of virtual double Ki67/synaptophysin staining, which not only addresses staining variation, but also helps in identifying tumor cells, facilitating a better distinction between tumor and non-tumor cells." (PMID 40730596, 2025). "Similarly, 14 years ago, the tumor cells exhibited positive staining for chromogranin A and synaptophysin." (PMID 40852171, 2025). "One of them highly expressed KI-67 and synaptophysin, suggesting that this tumor is of SCLC type." (PMID 39272828, 2024). "Histopathological examination of the biopsy sample is necessary to confirm the neuroendocrine nature of the tumor, usually characterized by uniform cells with neuroendocrine differentiation on immunohistochemical staining, positive for markers such as CgA and synaptophysin." (PMID 39233931, 2024). "In addition, synaptophysin in both tumor components of the current case, which supports the diagnosis of NET since in adenocarcinoma with endocrine cell differentiation endocrine cells are scattered within cancer nests." (PMID 38678248, 2024).